C3 (complement C3)
Diseases named in the same sentence as C3 in open-access papers (continued):
Sharing a sentence is not in itself a finding about the gene and the disease.
asthma (continued). "In different murine models of asthma, deletion of C3 or C3aR resulted in a restrictive effect on airways hypersensitivity, albeit with contradictory data regarding their role in the inflammatory reaction, that leads to asthma development." (PMID 38178176, 2024). "It was considered that complement C3 is positively correlated with asthma." (PMID 36071874, 2022). "Some C3 proteins are highly associated with asthma, such as: CD80 influences synthesis of IL-4 and IFN in non-specific bronchial asthma, mutations in IL12A influence cockroach allergy among children with asthma, ADA polymorphisms are related to asthma." (PMID 33008305, 2020). "Notably, the C3 pathway has been shown to be involved in the development of Th2 responses in allergic inflammation, which is also reflected by the fact that C3a levels are found upregulated in individuals with respiratory allergies and asthma." (PMID 32246830, 2020). "How they may be involved in the anti-inflammatory effects ascribed to raw milk remains unclear, although the complement pathway, and specifically C3, has been implied in the development of allergy and asthma." (PMID 28858242, 2017). "In patients with asthma, increased levels of serum C3 have been described." (PMID 22567103, 2012). "Recent studies have shown that patients with asthma have increased activation of complement components C3 and C5 with increased bronchalveolar lavage C3a and C5a levels following allergen challenge and patients with severe asthma have higher C3a plasma levels than those with stable asthma." (PMID 17044927, 2006). "Furthermore, IgG, IgA, tIgE, and C3 levels in serum were lower than those in the asthma group." (PMID 37893483, 2023). "In addition, a positive correlation between C3 levels and asthma severity has been described." (PMID 32246830, 2020). "Thus, having asthma may provide a source of C3, raising the probability that locally produced C3 may precipitate VEGF release and CNV development." (PMID 22567103, 2012). "Differentially methylated loci were near genes related to asthma (ITPR2, MAPK1), lung function (FKBP11), mitochondrial function (MRPL20, SPTBN1), inflammation (C3), and immune function (N4BP3, EIF5)." (PMID 41749276, 2026). "Various asthma triggers — such as HDM, ozone, cigarette smoke, viruses, and pollutants — activate C3, drive type 2 inflammation, and promote airway hyperresponsiveness (AHR) in a C3-dependent manner in mouse models." (PMID 40309766, 2025). "The most influential nodes (Fn1, Igf1, Ccl2, C3, Timp1, Cxcl12, Ccl4, Ccr2, Spp1, C3ar1, Cat, Cyp2e1, Muc5ac, Muc5b) were selected for further validation in the OVA-induced asthma and post-asthmatic fibrosis murine model." (PMID 35625754, 2022). "For unconfirmed C3 proteins in this module, its relationship with asthma has not yet been found, and we have suggested this possibility through enrichment analysis and provided clues for the diagnosis and treatment of asthma." (PMID 33008305, 2020). "We also found that asthma may affect the development of CNV, by increasing the protein levels of C3 and VEGF in the RPE/choroid layers, as observed in a rat model of allergic asthma." (PMID 22567103, 2012). "We found an increase in the levels of the C3 split products (113 kDa for C3α-chain and 106 kDa for C3α’-chain) and VEGF (51 kDa) in rats with asthma compared to rats without asthma." (PMID 22567103, 2012). "Our study showed higher levels of C3 and VEGF in rats with asthma compared to rats without asthma." (PMID 22567103, 2012).
membranoproliferative glomerulonephritis (33 papers, 2007 to 2026). Inflammation of the glomeruli characterized by deposits at the intraglomerular mesangium, resulting in thickening of the glomerular basement membrane, activation of complement, and impaired kidney function secondary to damaged glomeruli. "The second case with an immune-mediated condition affecting complement developed IMD in 2012 and was diagnosed with membranoproliferative glomerulonephritis associated with persistently low complement factors C3 and C4 four months later." (PMID 31200658, 2019). "Many patients with congenital lipodystrophy have low C3 levels associated with mesangiocapillary glomerulonephritis." (PMID 21274335, 2010). "This disease, which affects mainly women, is, at least for some patients, of autoimmune origin and may be associated with membranoproliferative glomerulonephritis, low serum levels of complement component C3 and/or the presence of C3-nephritic factor." (PMID 38678257, 2024). "One third of patients presented membranoproliferative glomerulonephritis and associated signs of activation of alternative complement pathway—the reduction of circulating concentrations of complement-component 3 (C3), and the presence of the C3-nephritic factor." (PMID 26987365, 2016). "A recent study indicated that factor H inhibits the alternative pathway of complement activation, and a critical regulator of C3 activation in vivo, as well as factor H-deficient mice (Cfh-/-) mice spontaneously develop membranoproliferative glomerulonephritis (MPGN) that depends on C3 activation." (PMID 17356516, 2007). "For example, membranoproliferative glomerulonephritis (MPGN) is characterized by the accumulation of C3 in the glomerular basement membrane." (PMID 38921822, 2024). "A renal biopsy confirmed a diagnosis of monoclonal membranoproliferative glomerulonephritis with granular IgG and C3 deposits of various sizes." (PMID 39301111, 2024). "We report the clinical and histological outcomes of two patients with biopsy-proven MGRS: one patient showed membranoproliferative glomerulonephritis with monoclonal k-light chain and C3 deposits, the second patient showed immunotactoid glomerulopathy." (PMID 33392216, 2020). "Renal biopsy revealed mesangiocapillary glomerulonephritis in 18.5% of them, while IF showed granular deposits of IgA and C3, and EM demonstrated electron-dense deposits in the mesangium." (PMID 29237409, 2017). "Membranoproliferative glomerulonephritis with deposits of C3, IgM, and IgG is the most frequent renal pathological finding of shunt nephritis." (PMID 27036403, 2016). "Their renal biopsy revealed membranoproliferative glomerulonephritis with positive C3 deposition." (PMID 27036403, 2016). "A kidney biopsy revealed a membrano-proliferative glomerulonephritis (MPGN), with a “full-house” pattern of endo-membranous deposits comprising IgA (+or-), IgM (++), IgG (+), C3 (++), C1q (+or-)." (PMID 32646497, 2020). "The reported native kidney biopsy diagnosis was membranoproliferative glomerulonephritis (MPGN) with IgG, C3 and kappa restricted deposits." (PMID 30764798, 2019). "The diagnosis on the native kidney biopsy performed 7 years before transplant was membranoproliferative glomerulonephritis (MPGN) with IgG, C3 and kappa restricted deposits and patchy interstitial fibrosis." (PMID 30764798, 2019). "Renal biopsy revealed membranoproliferative glomerulonephritis (MPGN) with IgM and weak C3 deposition." (PMID 26370133, 2015). "However, patients with C3GN usually have membranoproliferative glomerulonephritis (MPGN) on LM and low serum C3." (PMID 40851714, 2025).
ovarian carcinoma (33 papers, 2005 to 2025). A malignant neoplasm originating from the surface ovarian epithelium. "C3 is the precursor of C3a and has been detected at the primary tumor site in the serum of several solid cancers and is associated with poor prognosis in colorectal and ovarian cancer." (PMID 37174113, 2023). "Tumor cells were shown to secrete C3 in a syngeneic mouse model of ovarian cancer and cancer cell lines, and C3 deposition was found in tumors resected from C3-deficient mice." (PMID 31787848, 2019). "As far as treatment is concerned, C3 inhibitors have entered clinical trials in anti-ovarian cancer therapy and treatment against inflammatory bowel disease." (PMID 40698088, 2025). "Similar to CNC, ovarian cancer cells secrete C3, which is induced in these cells by the EMT factor Twist1 and is expressed at the invasive edge of metastatic cells in vivo." (PMID 37489330, 2023). "By contrast, reduced expression of C3 was observed in the blood of ovarian cancer patients, and this factor was downregulated in the serum of platinum-resistant patients." (PMID 34359708, 2021). "Circulating polymorphonuclear cells from ovarian cancer patients can acquire an immunosuppressive phenotype capable of restraining T-cell proliferation after exposure to ascites in a process dependent on C3." (PMID 34359708, 2021). "Some studies have used the syngeneic intraperitoneal injection of ID-8-MOSEC, a mouse epithelial ovarian cancer cell line originating in C57BL/6 mice, to evaluate the roles of C3, C5, and C5aR1 in ovarian cancer development and progression." (PMID 34359708, 2021). "In a transgenic mouse model of ovarian cancer, complement inhibition by C3 or C5aR knockout inhibited tumor growth by altering endothelial cell function and vascular endothelial growth factor (VEGF) expression." (PMID 31787848, 2019). "Secretion of Complement C3 protein in ovarian cancer cells promotes cell proliferation, invasion, and migration." (PMID 29721183, 2018). "Recently, an autocrine effect of complement proteins has been shown; specifically, C3 and C5 are secreted by ovarian cancer cells on tumor growth." (PMID 26540631, 2015). "Interestingly, previous studies revealed that the high expression of ABCA1, APLP2, C3, EPHA2, and EFNA1 were associated with poor prognosis and epithelial ovarian cancer progression." (PMID 39135097, 2024). "Moreover, it was reported that in a model of ovarian cancer, C3 silencing in cancer cells reduced the microvessel density in tumors." (PMID 37296948, 2023). "Ovarian cancer cells can secret C3, which promotes tumor growth and metastasis." (PMID 34722636, 2021). "Furthermore, ascitic fluid taken from ovarian cancer patients showed surface deposition of C3 with increased CFH (which is only mildly overexpressed in these cells in our dataset)." (PMID 30383866, 2018). "Finally, quantification of C3 mRNA in tumors from patients with ovarian cancer showed that overall survival in patients with low tumor expression of C3 was more than double that of patients with high expression of C3 in the tumor." (PMID 30687327, 2018). "Elevated levels of C3 are present in patients with ovarian cancer." (PMID 28938643, 2017). "Similarly, in ovarian cancer mice models (C57BL/6), the C3a-C3aR interaction triggers PI3K/AKT pathway activation, enhancing C3 secretion, tumor growth, and proliferation via a C3-dependent autocrine loop." (PMID 40370471, 2025).
renal failure (33 papers, 2010 to 2026). "Mesangial C3 deposition ≥ 2 + combined with hypocomplementemia (C3 < 90 mg/dl) was an independent risk factor for a 30% decline in eGFR or kidney failure during follow-up." (PMID 36348077, 2023). "This is the first retrospective study to explore the relationship between serum C3 levels measured at diagnosis and the risk of kidney failure in patients with anti-GBM disease." (PMID 35874697, 2022). "The results showed that C3 level was linearly correlated with the changing trend of kidney failure risk (p = 0.001), which means that as C3 levels increase, the risk of kidney failure occurrence gradually decreases." (PMID 35874697, 2022). "Decreased serum C3 level was associated with more severe renal insufficiency, higher glomerular histology grading, and poorer renal outcomes, though it failed to be an independent risk factor in T2D patients with DKD." (PMID 34806406, 2022). "The galactose-deficient IgA1/C3 ratio had a much stronger association with disease progression than either marker alone, and the risk of kidney failure increased continuously with the ratio." (PMID 34682837, 2021). "Also, high expression of C1q, C3, and C5b-9 in glomeruli was linked to the progression of kidney failure, whereas glomerular MBL was rare and unrelated to renal survival." (PMID 35479942, 2022). "Univariate analysis showed that C3 is markedly correlated with the risk of kidney failure." (PMID 35874697, 2022). "Furthermore, serum C3 levels were significantly associated with progression to kidney failure, but the predictive value of serum C3 was lower than clinical markers such as proteinuria and eGFR." (PMID 34682837, 2021). "In our small case series, dialysis was required in 72% of patients, of whom 36% progressed to kidney failure and requiring kidney transplantation, although 64% exhibited low C3 levels." (PMID 39347991, 2025). "Case 1 was a 69-year-old male presented with renal insufficiency and mild proteinuria, along with significant elevations of IgG, IgG4, eosinophils, and IgE, and severe reductions in complement C3 and C4." (PMID 40630956, 2025). "At the last follow-up, 83 patients progressed into kidney failure, of which 26 were in the low C3 group and 57 (84%) were in the normal C3 group." (PMID 35874697, 2022). "In addition, we found that serum albumin level was considered the prominent interactive factor that affects the association between C3 and the risk of kidney failure by the interaction analysis, which may be related to complement involvement in the pathogenesis of proteinuria." (PMID 35874697, 2022). "Cox regression and smooth curve fitting of generalized additive mixed model analysis were used to explore the correlation between serum C3 and kidney failure." (PMID 35874697, 2022). "Renal insufficiency (serum creatinine: 3.51 mg/dL, eGFR: 24 ml/min/1.73 m2), low serum C3 and C4 levels and hypergammaglobulinemia (4590 mg/dL) had already been found." (PMID 28446143, 2017). "Blood tests revealed renal insufficiency (serum creatinine: 1.6 mg/dL, eGFR: 48 ml/min/1.73 m2), low serum C3 and C4 levels and hypergammaglobulinemia (4250 mg/dL with oligoclonal banding)." (PMID 28446143, 2017). "A trend toward a decrease in C3 levels was also observed in patients who reached kidney failure." (PMID 36996481, 2023). "The results suggested that when the serum albumin <30 g/L, C3 had a protective effect on outcomes in patients with anti-GBM disease, and serum albumin could modify the relationship between C3 and kidney failure." (PMID 35874697, 2022). "Relationship between C3 and kidney failure under different stratification factors." (PMID 35874697, 2022). "Patients with high tubulointerstitial C1q, C3, C5b-9, and MBL levels were more likely to progress to kidney failure." (PMID 35479942, 2022). "Immunohistochemical analysis showed that patients with higher C1q, C3, C5b-9, MBL, or factor B expression in renal tubulointerstitium were more likely to progress to kidney failure." (PMID 35479942, 2022).
amyloidosis (32 papers, 2015 to 2025). A disorder characterized by the localized or diffuse accumulation of amyloid protein in various anatomic sites. "We recently demonstrated the presence of C3+-astrocytes associated with vascular amyloid deposits in the Tg-FDD model." (PMID 35351973, 2022). "Our data suggest that Tregs contribute to restrain the functional differentiation of pro-inflammatory C3-positive reactive astrocytes associated with advanced amyloid deposits, thus contributing to dampening detrimental neuroinflammation and cognitive deficits." (PMID 36890536, 2023). "FGN shows mesangial expansion with IgG, C3, and light chains, whereas amyloidosis features Congo red-positive, extracellular fibrils (7-15 nm) with apple-green birefringence." (PMID 40821257, 2025). "The complement system supports Aβ clearance through C3 interaction with SR-A, as C3 deletion increases amyloid burden in AD models." (PMID 41301546, 2025). "In a murine model of Alzheimer's-like amyloid pathology, Treg depletion was shown to alter reactive astrocyte subtype distribution, leading to an increase in C3-positive A1-like phenotypes." (PMID 40585999, 2025). "Next, our group evaluated the role of C3 in memory impairment during neuropathological changes in an amyloidosis mouse model, specifically in APPswe/PS1Δ9 mice." (PMID 38255891, 2024). "SRA proteins transthyretin, complement C3, albumin, fibrinogen, α-2-macroglobulin, fibronectin 1, and α-1-antitrypsin have been related to amyloidosis." (PMID 37902886, 2024). "Eight patients (21%) had low serum C3 level and normal serum C4 level including 1 amyloidosis patient, 3 cryoglobulinemic GN patients, 2 proliferative GN with monoclonal IgM deposits patients, 1 LCDD patient, and 1 C3 GN patient." (PMID 36216844, 2022). "Several studies have identified multiple complement proteins, such as C1q, C3 or C4, co-localizing with amyloid plaques not only in mouse models of AD but also in AD patients, suggesting a role of the complement system in AD." (PMID 35978440, 2022). "Furthermore, the disease-gene associations related to amyloidosis (Apolipoprotein E [APOE], C3, FGA, Transthyretin [TTR], and Serum amyloid P-component [APCS or SAMP]) showed significant enrichment (FDR = 2.66E-5)." (PMID 37875373, 2023). "We further confirmed the in vivo presence of these C3+ Decorin+ astrocytes and that these cells are associated with vascular amyloid but not with parenchymal amyloid deposits in mouse models and AD/CAA patients." (PMID 35351973, 2022). "Furthermore, deletion of C3 or suppression of C3 activation in multiple AD mouse models increased amyloid burden, indicating that complement is involved in amyloid clearance." (PMID 34002346, 2021). "More patients with PGNMID had low serum C3 levels than those with amyloidosis." (PMID 34217367, 2021). "A recent study testing effects of C3 deficiency in the APPPS1 model emphasised the dual-edged nature of complement; C3-deficient mice showed an increase in amyloid plaque load, in agreement with other studies, but were nevertheless protected against cognitive decline." (PMID 29134267, 2018). "In contrast, C3 has been shown to have beneficial effects in a mouse model of AD, which may be due to the enhancement of clearance of C3b-opsonized amyloid." (PMID 26914463, 2016). "We assessed whether CSF amyloid influences the relationship between CSF C3 and CSF ptau by statistically testing two theoretical models." (PMID 27357286, 2016). "Furthermore, as shown in vivo and in vitro, C/EBPD is an important driver of the expression of the acute phase response genes C3 and Saa3 in the amyloid-affected CNS." (PMID 26230261, 2015). "Besides, deficiency in C3 seems to protect against cognitive decline in a mouse model of AD-like amyloid pathology, suggesting C3 as another factor secreted by A1-like astrocytes that could potentially contribute to their neurotoxicity." (PMID 36890536, 2023).